BRAF (B-Raf proto-oncogene, serine/threonine kinase)
Diseases named in the same sentence as BRAF in open-access papers (continued):
Sharing a sentence is not in itself a finding about the gene and the disease.
Erdheim-Chester disease (35 papers, 2014 to 2026). "In contrast, LCH and Erdheim-Chester disease are neoplastic histiocytic disorders driven largely by the BRAF V600E mutation." (PMID 40398847, 2025). "In Erdheim-Chester disease, the BRAF V600E mutation is frequently observed; however, testing for this specific mutation revealed a wild-type result." (PMID 38813357, 2024). "In the past decade, BRAF V600E mutations have been reported in Erdheim Chester disease (ECD) and LCH, a significant advancement with treatment implications in these closely related diseases." (PMID 39735017, 2024). "The FDA also approved vemurafenib for Erdheim-Chester Disease, another rare type of histiocytic neoplasm involving BRAF V600 mutation." (PMID 34116682, 2021). "In November 2017, the FDA also granted approval for the use of vemurafenib in Erdheim-Chester Disease, a rare type of histiocytic neoplasm, with BRAF V600 mutations." (PMID 30975211, 2019). "Recently published literature have described an association between Erdheim-Chester disease and BRAF V600E mutation." (PMID 27995058, 2016). "In conjunction with the available literature, our findings indicate that neoplastic lesions related to LCH (e.g., Erdheim-Chester disease) also harbor BRAF mutations." (PMID 24938183, 2014). "Erdheim-Chester disease (ECD) is a rare histiocytosis with a high prevalence of BRAF V600E mutation (>50% of patients)." (PMID 25003820, 2014). "Furthermore, it is also FDA-approved for patients with Erdheim-Chester disease, which is a rare histiocytic disorder, that carry the BRAF V600E mutation." (PMID 36172151, 2022). "Erdheim-Chester disease (ECD) is a rare, multisystemic, idiopathic disease often associated with BRAF V600E mutation." (PMID 30942060, 2019). "Our findings show that vemurafenib therapy, even at low doses, can be effective for the treatment of intra-axial central nervous system involvement in BRAF-positive Erdheim-Chester disease." (PMID 25926131, 2015). "Orbital, chorioretinal, and multi-organ involvement of Erdheim-Chester disease, a rare non-Langerhans histiocytosis, with a negative BRAF mutation was diagnosed based on clinical, radiological, and pathological findings." (PMID 39298729, 2023). "Erdheim-Chester disease (ECD) is a rare non-Langerhans histiocytosis increasingly recognized as a clonal myeloid disorder driven by mutations in the mitogen-activated protein kinase (MAPK) signaling pathway—most notably the BRAF V600E mutation." (PMID 40726983, 2025). "An open-label nonrandomized study of 26 patients with BRAF V600–mutant LCH and Erdheim-Chester disease indicated that vemurafenib had prolonged efficacy, with a 62% confirmed overall response rate." (PMID 34093427, 2021).
endometrial cancer (33 papers, 2008 to 2025). Primary or metastatic malignant neoplasm involving the endometrium (mucous membrane that lines the endometrial cavity). "Of note, mutations in the KRAS, NRAS, and BRAF genes have also been reported in other human malignancies, e.g., colorectal and endometrial cancers." (PMID 39456660, 2024). "Only one study identified a relatively high frequency of BRAF mutations in endometrial cancers (21%), with an apparent overrepresentation in MLH1-deficient tumors (41% vs. 11% in pMMR tumors)." (PMID 33530449, 2021). "In line with the present study, we previously reported a low frequency (2%) of mutations in BRAF in endometrial cancer." (PMID 23300780, 2012). "Anyway, the clinical interest of BRAF mutation analysis in endometrial cancer is very unlikely." (PMID 33530449, 2021). "The detection of specific mutations in genes such as PTEN, PIK3R1, CTCF, and BRAF, which correlate with advanced disease features like high-grade tumors and deep myometrial infiltration, suggests that cfDNA analysis could become a crucial tool in the clinical management of endometrial cancer." (PMID 40227624, 2025). "In endometrial cancers, we have previously demonstrated that enhanced ERK signaling is triggered by constitutively active BRAF mutations." (PMID 36050359, 2022). "BRAF variants are rare in endometrial cancer and are not routinely assessed in the MMRd endometrial cancer." (PMID 38344144, 2023). "Moreover, a specific endogenous interaction between SPOP and BRAF was observed in Ishikawa endometrial cancer cells." (PMID 36585710, 2022). "In contrast to patients with colorectal cancers, patients with sporadic MSI MLH1 methylated endometrial carcinomas do not benefit from additional testing for V600E mutation of the BRAF gene as less than 1% display this mutation." (PMID 26161390, 2015). "Unlike colorectal carcinomas, somatic mutations in the BRAF gene resulting in sporadic cases are far rarer in endometrial carcinomas." (PMID 26161390, 2015). "BRAF mutation does not have a major role in endometrial cancers, thus is not included in this screening algorithm." (PMID 23531335, 2013). "However, studies of EC specimens show that BRAF mutation is very rare, thus BRAF mutation testing is not recommended in endometrial cancers when MLH1 loss is seen." (PMID 23531335, 2013). "Among them, the key players are PIK3CA, BRAF, and epidermal growth factor receptor (EGFR), which activate various tumor cell signaling pathways in endometrial cancer cells." (PMID 35264951, 2022). "ARNT2 (Cluster 5), BRAF (Cluster 5), and PAK7 (Cluster 5) were mapped to “Renal cell carcinoma;” APC (Cluster 5), BRAF (Cluster 5), and GSK3B (Cluster 2) were mapped to “Endometrial cancer;” and APC (Cluster 5) and GSK3B (Cluster 2) were mapped to “Basal cell carcinoma” in our results." (PMID 28445522, 2017). "This is in consistent with a recent report showing that this pathway is frequently activated independent of the status of KRAS and BRAF in endometrioid-type endometrial cancer." (PMID 23820584, 2013). "Therefore, BRAF status in endometrial cancer is not a component of INT2GRATE." (PMID 38344144, 2023).
biliary tract cancer (32 papers, 2017 to 2025). "BRAF mutations are rare in biliary tract cancers (BTCs), predominantly found in intrahepatic cholangiocarcinomas (iCCAs) with an overall incidence of about 5% to 7%." (PMID 40332392, 2025). "Biliary tract tumors: BRAF V600E mutations are identified in about 5–7% of biliary tract cancers (BTCs), particularly more frequent in intrahepatic BTCs." (PMID 40332392, 2025). "Advances in treatment also cater to tumours with other specific mutations, such as BRAF V600E, which have shown benefits from targeted therapy with Dabrafenib plus Trametinib in patients with BRAF V600E-mutated biliary tract cancer in a Phase 2 ROAR study." (PMID 40723185, 2025). "BRAF gene mutations, particularly BRAF V600E, are reported in about 3% of biliary tract cancers, especially iCCA." (PMID 39065760, 2024). "BRAF V600E is a targetable mutation in biliary tract cancers, based on the results of the phase 2 basket trial, ROAR." (PMID 38791902, 2024). "The BRAF V600E mutation in biliary tract cancer is associated with a higher oncologic stage, resistance to systemic chemotherapy, and a lower survival rate." (PMID 38203635, 2023). "The first attempt at evaluating the possibility of targeting BRAF mutations in metastatic biliary tract cancers was a phase two basket trial." (PMID 36499450, 2022). "Dabrafenib, an inhibitor of BRAFV600E, also has been investigated in patients with BRAF-mutated biliary tract cancers." (PMID 36123339, 2022). "BRAF V600 mutations are seen in 5% of this tumor type and combination of dabrafenib and trametinib treatment have shown promising activity in patients with BRAF V600E-mutated biliary tract cancer." (PMID 35130943, 2022). "In BRAFV600F-mutated biliary tract cancer, dabrafenib (a BRAF inhibitor) plus trametinib combination treatment may be an effective treatment option." (PMID 38365721, 2024). "Dabrafenib plus trametinib was subsequently evaluated in ROAR, which was an open-label, single-arm, phase 2 basket study that included a biliary tract cancer cohort consisting of 43 patients with BRAF V600E-mutated, advanced biliary tract cancer with progression on prior therapy." (PMID 37895447, 2023). "BRAF mutations are infrequent in biliary tract cancers and almost exclusively found in ICC." (PMID 38203635, 2023). "In Rare Oncology Agnostic Research (ROAR) basket trial targeting solid tumors with BRAF V600E, 43 patients with BRAF V600E-mutated biliary tract cancer were enrolled and dabrafenib (BRAF inhibitor) plus trametinib (MEK inhibitor) showed 47% of ORR and 14 months of median OS." (PMID 36290850, 2022). "In addition, for patients with BRAFV600E-mutated biliary tract cancer, dual blockade of both BRAF (dabrafenib) and MEK (trametinib) have been considered as a promising treatment option from a phase 2, open-label, single-arm, multicenter basket trial." (PMID 35039066, 2022). "Secondly, results for patients with BRAF V600E-mutated biliary tract cancer were published in 2020." (PMID 35955671, 2022). "Other promising targets for biliary tract cancers include mutations in IDH1 and IDH2, for which specific inhibitors like ivosidenib and enasidenib are available, as well as the BRAF V600E mutation." (PMID 39065760, 2024). "In the ROAR trial, 626 patients with biliary tract cancer were prescreened for BRAF V600E and 57 patients (9.1%) were found to harbor this variant." (PMID 36290850, 2022). "Actionable mutations for biliary tract cancer include HER2, BRAF V600E, NTRK fusion, and RAS." (PMID 40710208, 2025). "In gastrointestinal cancers, dabrafenib and trametinib have shown remarkable results in biliary tract cancers (BTC), establishing this combination as a viable second-line option for BRAF V600E-mutant BTC." (PMID 41646490, 2025). "Likewise, genetic alterations in biliary tract cancers can be directed toward targets involving IDH1, FGFR2, and v-raf murine sarcoma viral oncogene homolog B1 (BRAF)." (PMID 38893067, 2024).
biliary tract cancer (continued). "When looking at non-CRC GI malignancies, biliary tract cancers were found to have the highest frequency of BRAF alteration in 4.1% of patients, which is comparable to prior studies reporting a frequency of 5–7%." (PMID 38791902, 2024).
neuroblastoma (32 papers, 2012 to 2026). Neuroblastoma (NB) is the most common solid, extracranial childhood tumor. "It is wrongly activated and inhibits apoptosis due to different abnormalities like B-Raf proto-oncogene (BRAF) and neuroblastoma-RAS mutations." (PMID 38022807, 2023). "All patients progressed quickly after one cycle of treatment, except for one patient with neuroblastoma who displayed a BRAF G469A mutation and was treated with trametinib on compassionate access." (PMID 35681754, 2022). "Single mutations in the RAS-MAPK pathway are uncommon in neuroblastoma tumors at the time of initial diagnosis, with mutations of BRAF seen in approximately 1% of tumors and other RAS-MAPK pathway mutations only found in approximately 3–5%." (PMID 31695841, 2019). "TT sensitivity predictors were identified in 120/304 cases (39.5%): Tier II in 83 patients, Tier IB in 32 patients (almost always ALK in neuroblastoma, n = 31) and Tier IA in 5 patients: BRAF p.V600E (n = 3) and NF1 aberrations (n = 2)." (PMID 41373618, 2025). "Two patients with neuroblastoma harboring, respectively, an NF1 mutation and BRAF mutation were treated with trametinib." (PMID 35681754, 2022). "In vivo and in vitro dabrafenib was used to treat NBL patients with BRAF V600 mutation and SHP2 inhibitors combined with vemurafenib could treat relapsed neuroblastoma." (PMID 34745201, 2021). "Other rat sarcoma (RAS) mutations (specifically KRAS exon 3 and 4, and neuroblastoma (N]RAS) and v-raf murine sarcoma viral oncogene homolog B1 (BRAF) mutations may similarly reduce the benefit of anti-EGFR therapies." (PMID 34298750, 2021). "Clinical trials with MEK inhibitors for neuroblastoma are ongoing (NCT06104488 and NCT02124772) in single treatment or in combination with CDK4/6 inhibitor ribociclib and BRAF inhibitor dabrafenib." (PMID 40854877, 2025). "This includes the use of MEK inhibitors in relapsed CNS tumors with BRAF fusion, use of crizotinib, or other ALK inhibitors in relapsed neuroblastoma with an ALK alteration, and the use of imatinib and dasatinib in Ph (+) ALL." (PMID 31133068, 2019). "Similar to previous studies, our results indicated that BRAF/MEK/ERK signaling positively regulates Gli1 transcriptional activity in neuroblastoma cells (data not shown)." (PMID 23900341, 2013). "Moreover, by whole exome sequencing, we demonstrated that NB exo-DNA represents the entire exome and that it carries tumor-specific genetic mutations, including those occurring on known oncogenes and tumor suppressor genes in neuroblastoma (ALK, CHD5, SHANK2, PHOX2B, TERT, FGFR1, and BRAF)." (PMID 33915956, 2021).
cardio-facio-cutaneous syndrome (31 papers, 2010 to 2025). "BRAF gene mutations can cause birth defects in cardiofaciocutaneous syndrome, which is characterized by heart defects, mental retardation, and facial changes." (PMID 38674026, 2024). "Costello syndrome(CS) has been associated with mutations in HRAS, and cardio-facio-cutaneous syndrome(CFCS) with BRAF, MAP2K1, MAP2K2 and KRAS." (PMID 37964950, 2023). "Cardio-facio-cutaneous syndrome (CFC) is an autosomal dominant disease that occurs as a consequence of de novo heterozygous mutations in the BRAF, MAP2K1, MAP2K2 and KRAS genes." (PMID 36982349, 2023). "The patient was diagnosed with CFC syndrome by whole exome sequencing which picked up a BRAF gene mutation." (PMID 36938251, 2023). "Whole-exome sequencing picked up a BRAF gene mutation, and the patient was diagnosed with cardiofaciocutaneous syndrome." (PMID 36938251, 2023). "So is an HRAS-mutation definitively associated with Costello syndrome, and is a BRAF-mutation moderately associated with NS and definitively associated with cardiofaciocutaneous syndrome." (PMID 32394265, 2020). "We describe a girl with clinical signs of cardiofaciocutaneous syndrome who simultaneously presents a mutation in the BRAF gene and a 9p24.3 microduplication." (PMID 32185055, 2020). "The deleted region in this case contains 50 genes including the BRAF; the mutation of which is known to be associated with cardiofaciocutaneous (CFC) syndrome, a disease characterized by heart defects, mental retardation and a distinctive facial appearance." (PMID 29416564, 2018). "The BRAF variant c1495A>G p.(Lys499Glu) causes an amino acid change from Lys to Glu at position 499; this variant has previously been described as disease-causing in CFC syndrome." (PMID 36938251, 2023). "Among the recent examples: iPSC model of cardio-facio-cutaneous syndrome (CFCS) resulting from germline mutations in BRAF, enabled to show that differentiation of mutated iPSCs towards CMs leads to fibroblast-like cells that influence CM hypertrophy through TGFβ." (PMID 37349842, 2023). "The BRAF variant c1495A>G p.(Lys499Glu) causes an amino acid change from Lys to Glu at position 499; this variant has previously been described as disease-causing in cardiofaciocutaneous syndrome." (PMID 36938251, 2023). "In addition, a patient who carried a hotspot mutation in the BRAF gene was diagnosed with NS instead of cardiofaciocutaneous syndrome (CFCS)." (PMID 29084544, 2017). "Intriguingly, the BRAF CFC syndrome mutations are both kinase-active and kinase impaired in vitro." (PMID 20540792, 2010). "High and narrow palate with submucous clefting is a typical craniofacial feature in cardiofaciocutaneous syndrome, which is caused by mutations in KRAS, BRAF, MAP2K1 and MAP2K2." (PMID 34897389, 2022). "Four genes are known to be led to CFCS syndrome, namely, BRAF (~75%), MAP2K and MAP2K2 (~25%), and KRAS (<2%)." (PMID 29084544, 2017). "Constitutive active mutations in more downstream genes such as KRAS and BRAF result in an increased activation of the MAPK/ERK pathway and hence in short stature syndromes as for example Noonan or cardio-facio-cutaneous syndrome." (PMID 23155469, 2012). "Children with germ-line mutations in KRAS, BRAF, MEK1 and MEK2 develop Cardio-facio-cutaneous syndrome (CFC), characterized by abnormal heart, craniofacial, and skin development." (PMID 20540792, 2010).
small cell lung carcinoma (29 papers, 2009 to 2026). Small cell lung cancer (SCLC) is a highly aggressive malignant neoplasm, accounting for 10-15% of lung cancer cases, characterized byrapid growth, and early metastasis. "Two other possible mechanisms of resistance were detected in our population: transformation into small-cell lung cancer, and a BRAF mutation." (PMID 29100434, 2017). "The authors categorize resistance into EGFR-dependent mechanisms (e.g., secondary mutations like T790M and C797S), bypass pathway activation (e.g., MET or HER2 amplification, KRAS mutations, and BRAF mutations), and histologic transformation (e.g., small-cell lung cancer)." (PMID 40416863, 2025). "We now know that activation of MET or HER2 amplification, acquisition of mutations in BRAF, PIK3CA, and KRAS, histological transformation to small cell lung cancer (SCLC), and epithelial-to-mesenchymal transition (EMT) are major reasons." (PMID 39497713, 2024). "For “off‐targets,” such as MET amplification/overexpression, HER2 amplification, BRAF mutation, RET fusion, small cell lung cancer (SCLC) transformation, and so forth, there have been a lot of research and exploration in this field." (PMID 38090373, 2023). "Additional mechanisms include amplification of the MET gene, PIK3CA mutation, BRAF mutation, epithelial-to-mesenchymal transition (EMT), and small cell lung cancer (SCLC) transformation." (PMID 27821131, 2016). "Alternative signaling pathways, such as MET amplification, may also be activated, as are other mechanisms such as HER2 amplification, PIK3CA, KRAS, BRAF, and small cell lung cancer transformation." (PMID 39231972, 2024). "In addition, downstream KRAS, BRAF and other activation mutations, HER2 mutation, MET amplification lead to bypass activation, PTEN lost, and transformation to small-cell lung cancer (SCLC), which are also the mechanisms of acquired drug resistance." (PMID 30930778, 2019). "In small cell lung cancer and cervical cancer no BRAF class 1 mutation could be identified, but the overall BRAF mutation frequencies in these cancer types were low (13 and 10, respectively)." (PMID 36275468, 2022). "In addition, other acquired resistance mechanism has been reported; including the development of small cell lung cancer or squamous cell transformation, second point mutations (D761Y or L747S), MET amplification, acquired PIK3CA or BRAF mutation, and epithelial-to-mesenchymal transition." (PMID 26862733, 2016). "For advanced squamous non-small cell lung cancer (NSCLC), V-Raf murine sarcoma viral oncogene homolog B1 (BRAF) fusions have not been evaluated as a therapeutic target." (PMID 41897642, 2026). "As a consequence of FGF2 stimulation, PKCε complex formation with BRAF and S6K2, but not with S6K1 and RAF-1, induced drug resistance in SCLC (small cell lung cancer) cells, HEK293 and U2OS cells." (PMID 34830951, 2021).